SLC9A6 (solute carrier family 9 member A6)
Diseases named in the same sentence as SLC9A6 in open-access papers (continued):
Sharing a sentence is not in itself a finding about the gene and the disease.
tauopathies (2 papers, 2025). "SLC9A6 loss‐of‐function mutations disrupt vesicular targeting and are linked to tau inclusions, implicating it in tauopathies." (PMID 41399158, 2025). "Continued investigation into the molecular and cellular underpinnings of SLC9A6 function will not only deepen our understanding of NDPACX but may also provide critical insights into converging mechanisms underlying Parkinsonian syndromes and tauopathies in general." (PMID 41357349, 2025). "Importantly, two older carriers developed CBD and atypical Parkinsonian syndrome, reinforcing the potential link between SLC9A6 and adult-onset tauopathies." (PMID 41357349, 2025).
COVID-19 (1 paper, 2025). A disease caused by infection with severe acute respiratory syndrome coronavirus 2. "The results demonstrated that SLC9A6 and GAS2L1 were also significantly differentially expressed in patients diagnosed with COVID-19." (PMID 39965013, 2025).
Hepatic steatosis (1 paper, 2024). Steatosis is a term used to denote lipid accumulation within hepatocytes. "Hepatic histologic examination revealed that circ‐SLC9A6 or SLC9A6‐126aa, but not mut‐circ‐SLC9A6, accelerated hepatic steatosis." (PMID 39107881, 2024).
lipid metabolism (1 paper, 2024). "Furthermore, liver tissues from patients with NAFLD also accumulate SLC9A6‐126aa derived from circ‐SLC9A6, suggesting a potential pathogenic role for this process in human lipid metabolism‐related disorders." (PMID 39107881, 2024).
lipid metabolism disorders (1 paper, 2024). "Next, we investigated whether the lipid metabolism disorders caused by circ‐SLC9A6 were dependent on SLC9A6‐126aa." (PMID 39107881, 2024). "Pharmacological inhibition of either the ERK or p38 pathway, especially combined inhibition, significantly ameliorated SLC9A6‐126aa‐induced lipid metabolism disorders." (PMID 39107881, 2024).
Lysosomal disease (1 paper, 2023). "Similar to the results from Slc9a6−/− mice, electron micrographs of the EBV‐LCLs from our two patients revealed an accumulation of lamellated membrane structures resembling storage bodies observed in some lysosomal diseases." (PMID 37381736, 2023).
metabolic syndrome (1 paper, 2024). A cluster of metabolic risk factors for CARDIOVASCULAR DISEASES and TYPE 2 DIABETES MELLITUS. "Compared with those in the HFD+vector group, mice injected with AAV9‐TBG‐circ‐SLC9A6 or AAV9‐TBG‐SLC9A6‐126aa exhibited more severe dyslipidemia; on the other hand, the levels of proteins associated with lipid homeostasis were unaltered in the mice injected with AAV9‐TBG‐mut‐circ‐SLC9A6." (PMID 39107881, 2024).
Niemann-Pick disease type C (1 paper, 2022). NPC is a complex lipid storage disease mainly characterized by the accumulation of unesterified cholesterol in the late endosomal/lysosomal compartment. "Neurofibrillary tangles in young patients are seen only in rare conditions such as Niemann–Pick’s disease type C, subacute sclerosing panencephalitis, and genetic syndromes linked to PLA2G6 and SLC9A6 mutations." (PMID 35563179, 2022).
sarcopenia (1 paper, 2024). Progressive decline in muscle mass due to aging which results in decreased functional capacity of muscles. "The clinical targeting of circ‐SLC9A6 and SLC9A6‐126aa in NAFLD may provide important insights into potential interventions for NAFLD‐related diseases such as type 2 diabetes, sarcopenia, and aging." (PMID 39107881, 2024).
steatosis (1 paper, 2024). Increased lipid within the cytoplasm of cells. "In our study, elevated SLC9A6‐126aa was associated with the severity of steatosis in NAFLD patients." (PMID 39107881, 2024). "Morphological examination and histological staining revealed that CD36 deficiency abrogated the increases in hepatic steatosis, inflammation and liver injury induced by SLC9A6‐126aa overexpression." (PMID 39107881, 2024). "Given the involvement of hepatocytes and Kupffer cells in the regulation of NAFLD, we isolated primary hepatocytes and Kupffer cells to further investigate the role of circ‐SLC9A6 in steatosis." (PMID 39107881, 2024).
type 2 diabetes (1 paper, 2024). "Given that H4K16ac is a key player in type 2 diabetes and ageing, it will be worthwhile to further investigate whether SLC9A6‐126aa/H4K16ac affects NAFLD‐related diseases." (PMID 39107881, 2024).
tumor (2 papers, 2017 to 2021). "The outcome of UALCAN showed that, except SLC9A4 and SLC9A6, the mRNA expression of other members prominently affected tumor stage and lymph node metastasis." (PMID 34759967, 2021).
genetic disorders (1 paper, 2021). "Recently, ESES had been reported in some genetic disorders, such as KCNQ2, ZEB2, and SLC9A6." (PMID 33897753, 2021).
metabolic disorders (1 paper, 2024). "The essential role of nuclear SLC9A6‐12aa in metabolic diseases requires further investigation." (PMID 39107881, 2024). "Considering the role of H4K16ac modification in promoting promoter activation by regulating nucleosome accessibility and its involvement in the epigenetic regulation of metabolic disorders, we hypothesized that H4K16ac modification might direct SLC9A6‐126aa to regulate CD36 transcription." (PMID 39107881, 2024).
SLC9A6 also shares sentences with these, for which no sentence is quoted: Ataxia (10 papers); neurological disease (8); neurodegenerative disease (5); neurodevelopmental disorder (5); Rett syndrome (4); breast carcinoma (2); cancer (2); epileptic encephalopathies (2); neuroblastoma (2); schizophrenia (2); X-linked intellectual disability (2); alcohol dependence (1); Anxiety (1); aspergillosis (1); behavioral disorder (1); cerebellar degeneration (1); cognitive decline (1); Encephalopathy (1); hearing loss (1); infection (1); Kleefstra syndrome (1); Landau-Kleffner syndrome (1); muscular dystrophy (1); neuroaxonal dystrophy (1); Neurodevelopmental delay (1); neuronal migration disorders (1); Obesity (1); proteinopathies (1); psychotic disorder (1); status epilepticus (1).
A further 1 disease shares a sentence with SLC9A6 in 1 paper.